MRE11 (MRE11 double strand break repair nuclease)
Diseases named in the same sentence as MRE11 in open-access papers (continued):
Sharing a sentence is not in itself a finding about the gene and the disease.
prostate carcinoma (12 papers, 2014 to 2026). A carcinoma that arises from epithelial cells of the prostate gland. "A high level of MRE11 expression in prostate cancer tissue has been associated with poor outcomes, including increased risk of recurrence and decreased overall survival." (PMID 36998466, 2023). "To test if OGT regulates MRE11 chromatin-association, we isolated nuclear/cytosolic- and chromatin-fractions from prostate cancer cells treated with CDK9 inhibitor in the presence and absence of the OGT inhibitor OSMI-4." (PMID 35164752, 2022). "To conclude, MRE11 mutations are rare in prostate cancer tumors, but appear to cause a specific molecular signature." (PMID 35164752, 2022). "Finally, we show that MRE11 and O-GlcNAc are enriched at the prostate cancer-specific small nucleotide polymorphic sites, and the loss of MRE11 activity results in a hyper-mutator phenotype in patient tumors." (PMID 35164752, 2022). "Finally, MRE11 and O-GlcNAc chromatin binding sites overlap with the common prostate cancer small nucleotide polymorphic-loci, and the loss of MRE11 activity is associated with the hyper-mutator phenotype in prostate cancer patient samples." (PMID 35164752, 2022). "Interestingly though, MRE11 gene has truncating mutations in a subset of metastatic prostate cancer patient samples, and any of these truncating mutations are associated with a hyper-mutator phenotype of the tumor." (PMID 35164752, 2022). "In TALAPRO-1 phase 2 trial of talazoparib, a stable disease was achieved in patients with metastatic castration-resistant prostate cancers carrying the alterations in rarer HR repair genes including MRE11 and NBN." (PMID 36982687, 2023). "A combined therapy with olaparib and double immunotherapy (durvalumab and tremelimumab) showed its efficacy in patients with alterations in HR repair genes (including NBN, RAD50 and MRE11) in breast, ovarian, pancreatic, endometrial, or prostate cancers." (PMID 36982687, 2023). "Mirin inhibits MRE11 activity and seems to inhibit androgen-dependent transcription and thus replication of tumor cells in prostate cancer." (PMID 36998466, 2023). "Prostate cancer specific SNPs are bound by MRE11 and O-GlcNAc at different levels, which we propose to represent the temporal separation in the chromatin-arrival of OGT and MRE11 during DNA repair." (PMID 35164752, 2022). "Combined inhibition of CDK9 and OGT or MRE11 further decreases RNA polymerase II activity, induces DNA damage signaling, and blocks the survival of prostate cancer cells." (PMID 35164752, 2022). "Accordingly, we show that combined inhibition of CDK9 and either OGT or MRE11 induces robust DNA damage in prostate cancer cells." (PMID 35164752, 2022). "In prostate cancer specific SNPs, most of the loci are marked either by MRE11, O-GlcNAc or both, which likely represents the temporal separation in the chromatin-arrival of OGT and MRE11 during the DNA repair-process." (PMID 35164752, 2022). "Elevated expression of MRE11 also correlates with gastric cancer, colon cancer, and prostate cancer, conferring poor prognosis." (PMID 34440334, 2021). "In general, MRE11 expression is increased in prostate cancer." (PMID 35164752, 2022). "As a result, beyond the impact of MRE11 phosphorylation on cell-cycle checkpoints and DNA repair, Rsk-mediated phosphorylation of MRE11 may serve as a promising target for prostate cancer therapy." (PMID 34440334, 2021). "The finding that androgen-induced expression of FKBP5 was inhibited by mirin in all three cell lines argues that MRE11 complex function is critical for transcription in prostate cancer cells, which is consistent with the siRNA results published by another group." (PMID 30305041, 2018). "MRE11 appears to be largely dispensable for the unperturbed transcription in prostate cancer cells because inhibition of MRE11 did not decrease RNA Pol II phosphorylation." (PMID 35164752, 2022).
prostate carcinoma (continued). "APE2 did not have a significant relationship with Mre11 or Rad50 in uterine nor prostate cancers." (PMID 32111912, 2020).
Fanconi anemia (11 papers, 2011 to 2025). Fanconi anemia (FA) is a hereditary DNA repair disorder characterized by progressive pancytopenia with bone marrow failure, variable congenital malformations and predisposition to develop hematological or solid tumors. "However, in Fanconi anemia patients, due to mutations in the Fanconi anemia proteins that protect nascent mitochondrial DNA, MRE11, which acts as a mitochondrial protector, will over-cleave nascent mitochondrial DNA and release it into the cytoplasm." (PMID 39759116, 2025). "The Fanconi anemia suppression gene can protect the stability of the mitochondrial replication fork, thus preventing cGAS-STING activation caused by mtDNA produced by meiotic recombination 11 homolog 1 (MRE11) nuclease degradation." (PMID 38312740, 2024). "It abolishes the recruitment of RAD51 at stalled forks in Fanconi anemia cells, thereby exposing the stalled forks to the nucleases MRE11 and DNA231." (PMID 35768579, 2022). "At stalled replication forks in human cells, DNA-end processing or end protection by Mre11 depends on protein partners, including breast cancer type 2 susceptibility protein (BRCA2) and Fanconi anemia (FA) proteins BRCA1 and FANCD1." (PMID 24062528, 2013). "Additionally, FXR1 can physically interact with MRE11, which our group has previously identified as important for R-loop suppression by the Fanconi Anemia pathway." (PMID 35666183, 2022). "HR operates during the S and G2 phases of the cell cycle and relies on many proteins including BRCA1 and BRCA2, proteins of the MNR complex (MRE11/RAD50/NBS1), CtIP, MRE11, RAD51, ATM, H2AX, PALB2, RPA, RAD52 and proteins of the Fanconi anemia pathway." (PMID 28250960, 2017). "This occurs through a non-nucleolytic function of MRE11 that is important for R-loop suppression by the Fanconi Anemia pathway." (PMID 31537797, 2019). "In addition, a recent study in Fanconi anemia cells showed that SLFN11 hinders the binding of the single-strand binding recombination protein RAD51 at stalled forks and destabilizes nascent DNA tracts, leading to degradation of the stalled forks by the nucleases MRE11 and DNA231." (PMID 35768579, 2022).
lung carcinoma (10 papers, 2013 to 2025). "Similarly, elevated MRE11 was also associated with disease progression, poor survival outcomes, and radioresistance in oral and lung cancer patients." (PMID 37173905, 2023). "In addition, MRE11 deficiency in lung cancer cells decreases their ability to recruit RAW 264.7 cells." (PMID 36547079, 2022). "Heterozygous NBS1 splicing mutation (IVS11+2insT) detected in sporadic gastric, colorectal and lung cancers led to defects in crucial binding to Mre11, Mdc1 and BRCA1, and caused impaired ATM phosphorylation in response to low-dose irradiation in the heterozygous state." (PMID 24349281, 2013). "In this study, we explored the novel role of MRE11 in the IL6/STAT3/CCL2 signaling pathway in lung cancer." (PMID 36547079, 2022). "After the knockdown of MRE11 in lung cancer cells, we discovered that IL-6 or the conditional medium of THP-1 cells can induce the mRNA expression of STAT3 downstream genes, including CCL2, in the control cells, but not in MRE11-knockdown lung cancer cells." (PMID 36547079, 2022). "The results suggest that MRE11 could regulate the microenvironment of lung cancer through the CCL2 pathway." (PMID 36547079, 2022). "More importantly, we believe that MRE11 might be a novel target for lung cancer diagnosis and treatment." (PMID 36547079, 2022). "We also investigated the effect of MRE11 on macrophage recruitment by lung cancer cells." (PMID 36547079, 2022). "Furthermore, DDR mutations, such as ATM, PTEN, MRE11, and FANCA mutations, have been found in a large proportion of lung cancer patients, as well as BRCA1/2 mutations in 5% of patients, justifying the administration of PARP inhibitors to lung cancer patients." (PMID 37682974, 2023). "Furthermore, MRE11 is a potential target for lung cancer therapy." (PMID 36547079, 2022). "The clastogenic effect of ionizing radiation (IR) and chemotherapy is impaired in high MRE11 expressing phenotypes of breast and lung cancers, with recent data suggesting that high MRE11 expression lung cancer phenotypes may be protected from endogenous tumor related replication stress." (PMID 33927349, 2021). "In lung cancer, the interaction of IQGAP3 with DNA repair protein Rad17 was essential for Rad17 expression and foci formation, the Mre11-Nbs1-Rad50 complex formation, and ATM/Chk2 and ATR/Chk1 pathways activation." (PMID 36275458, 2022). "The correlation of APE2 with Mre11 was positive in liver and lung cancers, and negative in breast and kidney cancers." (PMID 32111912, 2020). "Our results showed that CCL2 mRNA expression and CCL2 secretion could not be activated in MRE11-knockdown lung cancer cells after macrophage activation." (PMID 36547079, 2022). "The nuclease-independent role of MRE11 in promotion of EMT and metastasis in oral cancer cells was also tested and confirmed in lung cancer cells (data not shown)." (PMID 33927349, 2021).
endometrial cancer (9 papers, 2014 to 2023). Primary or metastatic malignant neoplasm involving the endometrium (mucous membrane that lines the endometrial cavity). "Whereas in colorectal and endometrial cancer, mutations in MRE11 resulting in reduced expression of MRE11 and impaired function of the MRN complex have been observed." (PMID 34809722, 2021). "For example, there is interesting evidence that patients with endometrial cancer and mutations in MRE11 could be treated with PARP inhibitors." (PMID 32668560, 2020). "Among the 521 endometrial carcinomas patients 30.7% (132/430) showed a complete loss of MRE11." (PMID 24927325, 2014). "This is consistent with recent studies, showing that somatic mutations in MRE11 are frequently detected in MSI-positive colorectal and endometrial cancers." (PMID 28073364, 2017). "Importantly, the biallelic mutations of MRE11 account for roughly 39% of MSI cancers, and across 70 MSI primary human cancers, MRE11 mutations occurred in 83.7 and 50% of colorectal and endometrial cancers, respectively." (PMID 36833239, 2023). "Our data suggest that loss of MRE11 in ovarian and endometrial cancer may predict sensitivity to PARP inhibitor in vitro and supports further investigation on MRE11 as a predictive biomarker for PARP inhibitor treatment." (PMID 28073364, 2017). "Based on these findings, we propose that MRE11 expression may be used as a potential predictive biomarker for the effectiveness of PARP inhibitor treatment in endometrial cancers with MSI." (PMID 24927325, 2014). "Immunohistochemical analysis of MRE11, RAD50, and NBS1 was successful in 456, 466, and 458 endometrial carcinomas, respectively, due to the lack of tumour tissue in some TMA spots." (PMID 24927325, 2014).
gastric cancer (8 papers, 2017 to 2025). A primary or metastatic malignant neoplasm involving the stomach. "MRE11, a protein known to play a vital role in DNA double-strand break repair, is associated with the prognosis of a variety of tumours, but there are few studies regarding the role of MRE11 in gastric carcinoma (GC)." (PMID 31221177, 2019). "MRE11 negativity is significantly higher in sporadic gastric cancer than in early-onset or familial gastric cancer." (PMID 31767017, 2019). "For instance, the poly (T) 11 region of MRE11, a protein of the MRN repair complex which is involved in the process of double-strand break (DSB) repair process and in DNA damage response signalling was found to contain mutations in 81% of the total MSI-H gastric cancer cases analysed." (PMID 28144288, 2017). "In gastric cancer research, Nijmegen breakage syndrome 1 (NBS1) K388la promotes binding to MRE11, enabling MRE11-RAD50-NBS1 complex formation and DNA damage repair." (PMID 40994548, 2025).
melanoma (8 papers, 2013 to 2025). A malignant, usually aggressive tumor composed of atypical, neoplastic melanocytes. "In melanoma cell lines, inhibition of Brn3a caused DNA double-strand breaks as evidenced by Mre11/Rad50-containing nuclear foci." (PMID 23666755, 2013). "Using RNA‐Seq data from the TCGA SKCM database, RAD50, NBS1, MRE11 and ATM expression were analysed in melanoma tissues." (PMID 34709752, 2021). "Accordingly, patients with metastatic stage III melanoma tumours had a significantly higher mRNA expression for RAD50, NBS1, MRE11 and ATM as compared to patients with primary melanoma." (PMID 34709752, 2021). "Other tested DNA sensors (Cgas, Sting, Ddx41, Dhx9, Dhx36, Lrrfip1, Mre11, and additionally Aim2, which is absent in melanoma cells) were expressed in macrophages but were not significantly upregulated after irradiation." (PMID 33202881, 2020). "To determine whether melanomas that have dysregulation of the MRN complex or ATM may be sensitive to PARP inhibitors, we performed independent knockouts of ATM, NBN, and MRE11 in 2 melanoma cell lines, MeWo (TWT) and A375 (BRAF-mutant), followed by olaparib cell viability assays." (PMID 38758740, 2024).
neuroblastoma (8 papers, 2018 to 2023). Neuroblastoma (NB) is the most common solid, extracranial childhood tumor. "Consistently, our data also add up that high MRE11 expression predicts very poor prognosis in high-risk neuroblastoma and that nanoparticle-mediated delivery of its pharmacological inhibitor mirin strongly impairs the growth of MNA tumor xenografts." (PMID 30166519, 2018). "Since we noticed that high MRE11 expression occurs in MNA neuroblastoma, we speculated that MRE11 function might be required to control MYCN-associated RS and DNA damage, in this tumor subset." (PMID 30166519, 2018). "In fact, pharmacological inhibition of MRE11 by mirin inhibited tumor growth of MYCN-amplified neuroblastoma xenografts." (PMID 34069817, 2021). "Here, we explored the involvement of MRE11 in neuroblastoma as a model for MYCN-driven tumors and addressed the possibility to target the MRN complex to trigger intolerable levels of RS-dependent DNA damage in MNA/high-risk tumors." (PMID 30166519, 2018). "In MYCN-amplified neuroblastoma cells, higher MRE11 expression predicts poorer prognosis." (PMID 31767017, 2019). "Upon depletion or inhibition of MRE11 by knockdown or use of mirin, the accumulation of replication stress and DNA damage can be induced and results in significant impairment of tumor growth in vivo, suggesting the potential role of MRE11 inhibition in treating MYCN-amplified neuroblastoma." (PMID 31767017, 2019). "Remarkably, decreasing MRE11 expression may eventually favor proliferation and colony-forming capabilities in non-MNA cells, which is consistent with very low MRE11 expression being associated with poor prognosis, in primary MNSC neuroblastomas." (PMID 30166519, 2018). "In neuroblastoma patients, alterations in DDR-associated genes, including MRE11, account for about 50% of the analyzed samples, and this defect may contribute to induction of synthetic lethality with PARP inhibitor, providing an opportunity for PARP inhibitor treatment." (PMID 31767017, 2019). "Pharmacological inhibition of MRE11, through encapsulation of the mirin drug in nanoparticles, induces accumulation of RS, impairment of tumor growth and apoptosis in MYCN-amplified neuroblastoma xenografts in vivo." (PMID 34201047, 2021). "MRE11 is essential to prevent deleterious accumulation of DNA damage and its increased expression in MYCN-amplified neuroblastoma is required to restrain MYCN-dependent RS." (PMID 34201047, 2021). "Therefore, in non-MYCN amplified neuroblastomas, the loss of MRE11 with the accompanying 11q deletion may contribute to poor prognosis as a consequence of their irregular DNA repair." (PMID 34069817, 2021). "The use of MRE11 exonuclease inhibitor mirin increased the RS and DNA damage biomarkers in MYCN-amplified neuroblastoma cells until death in vitro and induced apoptosis in vivo." (PMID 34201502, 2021). "Substantial evidence revealed that the frequency of allelic loss at 11q23 was inversely related to MYCN amplification in neuroblastomas, a common region of deletion that harbours a series of proteins that play a central role in the DSB repair pathways such as ATM, MRE11, and H2AFX." (PMID 37240360, 2023). "While the latest observation is consistent with the expected tumor suppressive role of MRE11, its high expression observed in bad prognosis and MNA neuroblastoma suggests it might be required for tumor growth, in this subset." (PMID 30166519, 2018). "Intriguingly, MRE11 is highly expressed and predicts bad prognosis in MYCN-amplified neuroblastoma." (PMID 30166519, 2018).
neuroblastoma (continued). "However, it was observed that MYCN is a transcriptional regulator of MRE11, RAD50, and NBS1, and the MRN complex contributes to the control of DNA damage levels compatible with tumor cell survival, so that high MRE11 expression is related to reduced overall survival in primary human neuroblastoma." (PMID 34201502, 2021).
glioma (7 papers, 2014 to 2025). A benign or malignant brain and spinal cord tumor that arises from glial cells (astrocytes, oligodendrocytes, ependymal cells). "MRE11, RTCB, TIMM9 and METTL14 were up‐regulated in gliomas, while CDPIT and MFN2 were down‐regulated." (PMID 35044082, 2022). "To address the relative roles of MRE11 and UBR5 in the TRF2-mediated control of telomeric fusion, we genetically suppressed MRE11 and UBR5 alone or in combination in alternative lengthening of telomeres (ALT)-dependent glioma cell lines." (PMID 34881184, 2021).
hereditary cancer (6 papers, 2014 to 2023). Malignant neoplasms occurring in families at a rate greater than that expected by chance and caused by germline mutations in a specific gene. "The MRE11 K255E mutation, in particular, has been identified in uterine endometrioid carcinoma (1/399, in cBioPortal database), and both K255E and K384Q/I mutations have been found in hereditary cancer-predisposing syndrome, but their intrinsic effect on cancer development is still unknown." (PMID 36050397, 2022).